CXCL10 (C-X-C motif chemokine ligand 10)
Diseases named in the same sentence as CXCL10 in open-access papers (continued):
Sharing a sentence is not in itself a finding about the gene and the disease.
malignant glioma (4 papers, 2014 to 2024). A grade III or grade IV glioma arising from the central nervous system. "This is the first study showing that the suppression of the CCL2/CCR2 and CXCL10/CXCR3 axes by celecoxib may attribute to antitumor effects in a mouse malignant glioma model, in addition to intrinsic and extrinsic apoptotic induction by celecoxib in GSCs." (PMID 32943658, 2020). "Regarding mouse malignant gliomas, when GL261 cancer cells were transfected with CXCL10 and subcutaneously transplanted into mice, tumor progression was significantly delayed, suggesting that the CXCL10/CXCR3 pathway can effectively inhibit tumor progression." (PMID 36479091, 2022). "Based on these findings, we hypothesized that in GSCs and a GSC-bearing malignant glioma model, modulation of the CCL2/CCR2 and CXCL10/CXCR3 axes by celecoxib might contribute to antitumor effects." (PMID 32943658, 2020).
malnutrition (4 papers, 2021 to 2025). Inadequate nutrition resulting from poor diet, malabsorption, or abnormal nutrient distribution. "In contrast, the concentration of CXCL10 in the duodenal luminal fluid from LPi mice was significantly decreased as a result of the interaction of both variables (malnutrition and infection) (p < 0.05)." (PMID 34207946, 2021). "Increased levels of duodenal IL-17A, IL-21, IL-22, CXCL5 due to malnutrition—together with decreased levels of TNFα, IL-12, TGFβ and CXCL10 and elevated levels of IgA due to infection—revealed that the duodenum was sensitive to both variables and suggested local inflammation in malnourished animals." (PMID 34207946, 2021).
neuritis (4 papers, 2020 to 2024). A neuropathy arising from inflammation of one or more nerves. "In patients with neuropathic pain, CXCL10 concentration were slightly elevated compared to those with neuritis." (PMID 38590701, 2024). "The concentrations of CCL-2/MCP-1, IFN-γ and, CXCL10 / IP-10 were slightly higher in patients with neuropathic pain, as opposed to those with neuritis." (PMID 32038662, 2020).
pancreatitis (4 papers, 2021 to 2024). Inflammation of the pancreas. "The CXCL10/CXCR3 signaling axis has been implicated in generating inflammation in various diseases including pancreatitis." (PMID 34328416, 2021). "CXCL10, also called interferon-γ inducible protein 10 (IP-10), is a chemokine expressed in many inflammatory diseases including pancreatitis." (PMID 35493517, 2022).
renal carcinoma (4 papers, 2016 to 2022). A carcinoma arising from the epithelium of the renal parenchyma or the renal pelvis. "CXCL10/IP-10 has a clear controlling role on immune response and inflammation and has been recently found to be involved in liver and renal cancer development." (PMID 27764787, 2016).
respiratory syncytial virus infection (4 papers, 2022 to 2025). "In contrast, in infants, higher levels of CXCL10 in nasal washes are associated with protection against severe respiratory syncytial virus infection." (PMID 41025782, 2025). "In line with our observation, it has previously been shown that respiratory syncytial virus infection was associated with a defective humoral response, which correlated positively with the levels of CXCL10, and that neutralizing CXCL10 improved ARDS." (PMID 36030261, 2022).
retinal degeneration (4 papers, 2017 to 2025). Degeneration of the retina. "Interestingly, among the cytokines overexpressed in our ocular models, CXCL10 has already been shown to be implicated in various ocular disorders involving retinal degeneration and has been shown to be up-regulated in human RPE and in the eyes of mice infected systemically with ZIKV." (PMID 32324736, 2020). "Several of these chemokines, including CCL2, CXCL1 and CXCL10 are involved in leukocyte recruitment in CNS diseases and in retinal degeneration." (PMID 28438165, 2017). "Chemokine expression is prominent in many retinal degenerations, including AMD, wherein the up-regulation of genes encoding potent ligands such as Ccl2 and Cxcl10 is a characteristic of the disease." (PMID 28438165, 2017).
scrapie (4 papers, 2016 to 2021). A fatal disease of the nervous system in sheep and goats, characterized by pruritus, debility, and locomotor incoordination. "In contrast, astroglial activation as assessed by IHC and by upregulation of Gfap and Cxcl10 appeared to be strong in both scrapie and BE infection." (PMID 27046083, 2016). "In the current study, none of the target genes (GFAP, SAA3, CXCL10, CD14, S100A9, and IL1B) associated with the acute phase response and inflammation were differentially expressed in the hippocampus of animals with and without scrapie." (PMID 31924264, 2020).
serous ovarian cancer (4 papers, 2020 to 2022). "Studies have shown that high CXCL10 concentrations in advanced serous ovarian cancer patients correlated with better survival through attraction and infiltration of T cells, thus encouraging the use of combinatorial treatments." (PMID 35997357, 2022). "In a mouse model of high-grade serous ovarian cancer, CXCL10 altered the tumor immune microenvironment and facilitated disease progression." (PMID 33763130, 2021). "In a retrospective cohort of patients with high-grade, serous ovarian cancer, the ratio of active: total CXCL10 discriminated malignant from non-malignant gynaecological disease samples with greater efficacy than CA125." (PMID 34200333, 2021).
skin cancer (4 papers, 2011 to 2025). "Consistent with M2-like macrophages in skin tumors, sub-cluster 2 showed high expression of M2-like macrophage markers, including Mgl2, Cx3cr1, Vcam1, Maf, Ccl8, and Cxcl10." (PMID 40282557, 2025). "Of note, our data showed a higher level of Cxcl10 and Ccl8 in the macrophage population in skin tumors." (PMID 40282557, 2025). "We will further investigate the mechanisms regulating DC subset migration into the TME during skin tumor progression and engineer a subset of DCs through Cxcl9/Cxcl10 to further improve the antitumor therapy." (PMID 40282557, 2025). "Further, we found a higher expression of Cxcl9, Cxcl10, and Dpp4 in DCs in skin tumors." (PMID 40282557, 2025). "Therefore, further studies on targeting Cxcl10 and Ccl8 secreted by macrophages may provide new prospects for skin cancer therapy." (PMID 40282557, 2025). "Our results show that a marked correlation between the CD103+DC signature (IRF8, FMS‐like tyrosine kinase 3 ligand, CLEC9A, CLNK, XCR1, BATF3, and ZBTB46) and chemokines C‐X‐C motif chemokine ligand 9, CXCL10, and CD8A in a mouse model with DMBA/TPA‐induced skin cancer." (PMID 36891351, 2023). "K17 is known to promote CXCL10 and CXCL11 expression in skin tumor keratinocytes." (PMID 38140561, 2023).
small cell lung carcinoma (4 papers, 2021 to 2023). Small cell lung cancer (SCLC) is a highly aggressive malignant neoplasm, accounting for 10-15% of lung cancer cases, characterized byrapid growth, and early metastasis. "For instance, the TCGA data of LUSC represented alteration frequency only for amplification type whereas UCOLOGENE 2015 revealed that alterations in CXCL10 of small cell lung cancer are completely mediated by mutation type genetic change." (PMID 33585826, 2021). "In a similar study, the Chk1 inhibitor SRA737 in combination with low dose gemcitabine increased CCL5, IFN-β and CXCL10 mRNA expression in small cell lung cancer again indicative of Chk1i activating a Type I IFN response." (PMID 35006469, 2021). "This current work is in direct contrast to previously published work demonstrating that Chk1 inhibition in small cell lung cancer cells increased TBK1 and IRF3 phosphorylation, CCL5, IFN-β and CXCL10 mRNA expression, and elevated PD-L1 expression all indicative of a type I IFN response." (PMID 35006469, 2021). "Moreover, small cell lung cancer research revealed that the CDK7 inhibitor YKL-5-124 activated CXCL9 and that CXCL10 signalling may be a promising outcome of combining YKL-5-124 and anti-PD-1, confirming the pivotal function of CXCL9 in immunotherapy." (PMID 34527583, 2021).
syphilis (4 papers, 2015 to 2018). A contagious bacterial infection caused by the spirochete Treponema pallidum. "Third, in patients co-infected with HIV and syphilis, the presence of CXCL13, CXCL10 and CXCL8 in CSF could be associated with syphilis, HIV or both." (PMID 27650493, 2016).
vitamin D deficiency (4 papers, 2017 to 2024). A nutritional condition produced by a deficiency of VITAMIN D in the diet, insufficient production of vitamin D in the skin, inadequate absorption of vitamin D from the diet, or abnormal conversion of vitamin D to its bioactive metabolites. "In patients with vitamin D deficiency, the increases in IL-6 and caspase-3 expression, alongside elevated levels of IL-1β and CXCL10, emphasize a pronounced inflammatory and apoptotic milieu." (PMID 39062991, 2024).
acne (3 papers, 2014 to 2024). An inflammatory process of the sebaceous glands which is characterized by comedones, nodules, papules and/or pustules on the skin. "All of these findings indicate that the expression levels of CXCL10 are elevated in rosacea and acne lesions, and its role in the pathogenesis of these two diseases requires further study." (PMID 38321132, 2024). "Similar results were observed in a cohort study, the CXCR3 ligands CXCL9, CXCL10, and CXCL11 were overexpressed in acne lesions." (PMID 38321132, 2024). "The expression of CXCL10, MMP9, IL1B, CXCL8, and CXCR4 were co-regulated by IRF1, STAT1, STAT3, IKBKB, HDAC1, ETS1, and CEBPB, which were highly expressed in rosacea and acne lesions." (PMID 38321132, 2024). "The relative roles of CXCL10 and CXCL13 on recruitment of specific T cell subsets in the context of acne pathogenesis will be of interest for future investigations." (PMID 34746181, 2021). "Similar findings were observed in the German cohort, since STAT1 a positive regulator of Th1 development was induced, and the CXCR3 ligands CXCL9, CXCL10 and CXCL11, were overexpressed in lesional acne skin." (PMID 25153527, 2014). "In acne lesions, all hub genes were negatively correlated with resting mast cells, whereas 9 (except CXCL10), 9 (except MMP9) and 8 (except MMP9 and CXCL10) hub genes were positively correlated with activated mast cells, gamma delta T cells, and neutrophils, respectively." (PMID 38321132, 2024).
acute GVHD (3 papers, 2013 to 2024). "The significant increase in the levels of CXCL9 and CXCL10 in patients’ plasma can serve as effective diagnostic biomarkers for acute GVHD." (PMID 39840040, 2024). "Furthermore, in acute GVHD mice treated with JAK inhibitors, a significant decrease in CXCL10 levels was observed, indicating that changes in chemokine levels can reflect the response of acute GVHD to effective therapy." (PMID 39840040, 2024). "Specifically, the upregulation of CXCL9, CXCL10, and CXCL11 in the skin of patients with acute GVHD promotes the recruitment of eosinophils and T cells to the sites of injury." (PMID 39840040, 2024).
Anosmia (3 papers, 2021 to 2025). An inability to perceive odors. "In addition, persistent inflammation evidenced by elevated levels of interleukin 6 (IL-6), type I interferon (IFN), and C-X-C motif chemokine ligand 10 (CXCL10) within the olfactory epithelium, secondary to invasion, appears to contribute to long-standing anosmia." (PMID 36899952, 2023).
aspergillosis (3 papers, 2011 to 2023). Aspergillosis is an infection, growth, or allergic response caused by the Aspergillus fungus. "Neutrophils are well known for their role in providing protection against invading fungal pathogens and their recruitment is dependent upon chemokine release, and polymorphisms resulting in CXCL10 expression changes have been found associated with aspergillosis." (PMID 36602962, 2023). "A delayed response to A. fumigatus could lead to increased susceptibility to aspergillosis; the significance of donor variability has been confirmed by the association of SNP in CXCL10 and an increased risk of IA." (PMID 21264256, 2011).
autoimmune Addison’s disease (3 papers, 2016 to 2022). "Interestingly, investigations into the role of type I IFNs in autoimmune Addison’s disease (AAD) show a similar CXCL10 finding between patients and healthy controls." (PMID 33859290, 2021). "With respect to adrenal autoimmunity, TLR3-expressing adrenocortical carcinoma cells stimulated with poly(I:C) along with IFN-γ or tumor necrosis factor α display significant rise in production of CXCL10, a chemokine involved in autoimmune adrenal failure." (PMID 26318769, 2016).
autoimmune encephalitis (3 papers, 2019 to 2022). Inflammation of the brain secondary to an immune response triggered by the body itself. "Studies in patients with NMDAR antibody-associated autoimmune encephalitis have shown an increase in serum IL-2 and CSF IL-6, IL-17, CXCL-10, and IL-1β." (PMID 36048783, 2022). "In addition, genes characteristic for the subset of Cxcl10+ and Saa3+ monocytes that arise under sterile inflammatory conditions (e.g., autoimmune encephalitis) were only upregulated in the listeria model." (PMID 36010615, 2022).
bacterial meningitis (3 papers, 2019 to 2024). Inflammation of the membranes surrounding the brain and spinal cord due to a bacterial infection. "In bacterial meningitis, multiple cytokines including CXCL10 (IP10), CCL2, CCL7 (MCP-3), CCL4 (MIP-1β), CCL5, CXCL12, IL6, IL8, and IL17 have been shown to be increased in the acute phase of the disease (; Pinto)." (PMID 31727097, 2019).
cholangitis (3 papers, 2018 to 2024). An acute or chronic inflammatory process affecting the biliary tract. "For example, testosterone suppressed hepatic inflammation by downregulating IL-17, CXCL9, and CXCL10 in an acute cholangitis model." (PMID 38338982, 2024). "We observed a more severe histopathological phenotype of cholangitis in absence of NLRP3, characterized by loss of bile ducts and larger inflammatory foci and higher levels of IL- 6 and CXCL10 as compared with NLRP3 sufficient mice." (PMID 32716024, 2020). "Therapeutic blockade of IL-15 in obese mice with cholangitis resulted in attenuated histological damage, lower numbers of infiltrating neutrophils and CD8+ T cells and reduced levels of proinflammatory cytokines and chemokines including IL-13, IL-17, C-GSF, CCL2, CCL3 and CXCL10." (PMID 29449577, 2018).
chronic GVHD (3 papers, 2018 to 2024). "Tear levels of epidermal growth factor and IP-10/CXCL10 are significantly decreased, while tear levels of interleukin-1Ra, IL-8/CXCL8, and IL-10 are significantly increased in patients with ocular chronic GVHD compared to healthy controls under controlled environmental conditions." (PMID 39200870, 2024). "Serum measures of CXCL1 and CXCL10 were induced in acute and chronic GVHD patients in compare to these without GVHD." (PMID 34711015, 2021).
cyst (3 papers, 2020 to 2024). A sac-like closed membranous structure that may be empty or contain fluid or amorphous material. "gondii during the acute stage of infection, we examined whether CXCL10 is involved in recruiting anti-cyst CD8+ cytotoxic T cells to eliminate the cysts in their brains." (PMID 39597561, 2024).
demyelinating disorders (3 papers, 2018 to 2023). "Another study in an experimental model of demyelinating disease found that CXCL10 deficiency resulted in reduced microglial activation and amelioration of chronic neurotoxicity." (PMID 37596685, 2023).
dysplasia (3 papers, 2021 to 2023). A usually neoplastic transformation of the cell, associated with altered architectural tissue patterns. "The transcript levels of Th1-associated chemokines/cytokines (Cxcl9, Cxcl10, Ccl5, and Ifng) and the Th1-associated chemokine receptor Cxcr3 were upregulated in dysplasia, whereas the expression of these Th1-associated genes was decreased in SCC." (PMID 33921389, 2021).
E. coli infection (3 papers, 2020 to 2025). "Our results showed that pretreatment with different doses of L. plantarum 17–5 reduced the expression of IL1β, IL6, IL8, TNFα, COX2, iNOS, CXCL2 and CXCL10 during E. coli infection." (PMID 35764986, 2022).
enterovirus infection (3 papers, 2020 to 2023). "They found that close association between VP1 and CXCL10 expression is not only detected in islet cells, but also in pancreatic exocrine ductal cells and acinar cells and concluded that enterovirus infection induced CXCL10 expression in both exocrine pancreas and islets." (PMID 33193102, 2020). "In contrast, in the infants with enterovirus infection increased levels of CXCL10 (IP-10), which is related to Th1 immunity and IL-17 were found after the infection, while CCL4 (MIP-1β) and CCL22 (MDC), remained decreased after enterovirus infection." (PMID 33643278, 2020). "The study on aseptic meningitis caused by nonpoliomyelitis enterovirus infection in children showed that the levels of CXCL10 and CXCL11 in CSF were higher than those in normal children, and CXCL10 levels may have high differential value to identify nonpolio aseptic aseptic meningitis." (PMID 37904697, 2023).
Fever (3 papers, 2007 to 2019). Body temperature elevated above the normal range. "All in all, the present study has identified IFN-α as a universal biomarker of human OROV fever, while CXCL8 & IL-5 and CXCL10 & IL-17 were observed consistently in early and late seroconverters, respectively." (PMID 31784575, 2019).
graft versus host disease (3 papers, 2018 to 2024). An immune system disorder that occurs after allogeneic hematopoietic stem cell transplant and is a reaction of donor immune cells against host tissues. "Interestingly, a recent study has shown increased CXCL-10 levels in the acute graft-versus-host disease (aGvHD) subsequent to bone marrow transplantation." (PMID 30305140, 2018).
H1N1 virus infection (3 papers, 2010 to 2024). "However, previous studies in vivo have also shown that CXCL10 potentially contributes to lung pathology of H1N1 virus infection." (PMID 21819625, 2011).
hematoma (3 papers, 2014 to 2023). A hematoma is a collection of blood from a vascular structure into an extravascular space. "Clinical studies have reported associations between serum inflammatory markers in the acute phase of ICH, mainly CCL2, CXCL10, IL-6, IL-11, CRP, fibrinogen, and CSF cytokines with hematoma expansion and early neurological decline." (PMID 34439789, 2021). "In the same study, a positive association between hematoma fluid CCL5 (also termed regulated on activation, normal T-cell expressed and secreted, RANTES) levels and recurrence as well as a negative association between IL-5, IL-13, IFN-γ and CXCL10 levels and recurrence was also indicated." (PMID 37510193, 2023).
hypoglycaemia (3 papers, 2021 to 2024). "Molecules such as CXCL10 and IL-6 have been reported to be involved in abnormal glucose metabolism by inhibition of hepatic gluconeogenesis decreasing the concentration of glycemia in the blood, which may explain our result in patients with hypoglycemia." (PMID 36178979, 2022). "Hypoglycemia was related to low IL-4, CXCL10, IL-6, and IFN-γ concentrations, regarding patients with normal glycemia concentrations." (PMID 36178979, 2022).
inclusion body myositis (3 papers, 2014 to 2023). A slowly progressive degenerative inflammatory disorder of skeletal muscles characterized by late onset weakness of specific muscles and distinctive histopathological features. "CXCL10 is abundantly expressed in macrophages and T cells surrounding and invading non necrotic muscle fibers in inclusion body myositis." (PMID 24939012, 2014).